INS (insulin)
Diseases named in the same sentence as INS in open-access papers (continued):
Sharing a sentence is not in itself a finding about the gene and the disease.
diabetes (continued). "Type-1 diabetes mellitus (T1DM) is a complex metabolic disorder characterized by chronic hyperglycemia following the destruction of pancreatic beta cells by the immune system and the complete lack of insulin." (PMID 36333733, 2022). "Similarly, Pertot and colleagues reported the lack of predictive power for insulin therapy for GDM using maternal characteristics including race/ethnicity, BMI, family history of diabetes, hemoglobin A1c, and glucose levels." (PMID 36104698, 2022). "Several clinical studies have reported that pancreatic fat content negatively correlates with insulin secretion, using magnetic resonance imaging and spectroscopy (MRI/S) and oral glucose tolerance tests (OGTT) in populations with and without diabetes, while others have not found such a correlation." (PMID 36584200, 2022). "In fact, an RCT on non-diabetic offspring whose parents have diabetes found that 8 weeks of yoga significantly reduced FPG levels, oral glucose tolerance test post-2 h glucose levels, fasting insulin levels, and insulin resistance, whereas the control group showed no significant changes (n = 57)." (PMID 35682203, 2022). "The higher rates of diabetes remission are seen in younger patients with higher preoperative BMI, lower HbA1c and FBS, with shorter duration of T2DM who were not insulin therapy, and not having a family history of obesity at 1-year and 3 years after bariatric surgery." (PMID 36289529, 2022). "Hence in this study, we assessed the correlation between the insulin-based HOMA-IR index and the C-peptide based HOMA-IR index in a group of people without diabetes living in a SSA urban setting." (PMID 36224640, 2022). "Type 2 diabetes mellitus (T2DM) is sometimes cited as non-insulin-dependent diabetes mellitus (NIDDM) as it occurs because of the inability of beta cells of the pancreas to secrete insulin, defects in insulin action, or both." (PMID 36295849, 2022). "For instance, Dave and Katyare (2002) observed that alloxan-induced diabetes in rats significantly increased the plasma and cardiac BCHE activities, which could not be reversed by insulin therapy." (PMID 35055468, 2022). "Patients with syndromic diabetes typically have a similar diabetes phenotype to MODY (young-onset diabetes, non-obese and have negative islet autoantibodies) but unlike MODY, they are more likely to be insulin treated." (PMID 34789499, 2022). "Diabetes mellitus (DM): PCSK9 could be positively correlated with the onset of DM, which is characterized by insulin resistance and a relative lack of insulin." (PMID 35806921, 2022). "However, the prescription of insulins to type 2 diabetes mellitus patients is often not in line with the guideline, which recommends NPH insulin as first choice and discourages newer insulins." (PMID 35698052, 2022). "The reduced tyrosine phosphorylation and increased serine/threonine phosphorylation of IRS-1 due to diabetes or obesity have mostly been considered to be negative regulators of IRS-1 function and are widely regarded as critical players in inhibiting insulin signaling." (PMID 36547071, 2022). "One study confirmed that plasma FFA kinetics may be dysregulated due to changes in circulating insulin and glucose in PCOS patients without diabetes, particularly obese patients, which may be related to insulin sensitivity." (PMID 36017313, 2022). "We cross-sectionally recruited 79 men with non-insulin-treated T2DM and no known liver diseases, who had consecutively attended our diabetes outpatient service over a 6-month period and who underwent both ultrasonography and Fibroscan-measured liver stiffness (LSM)." (PMID 35831700, 2022). "Our results from 113 people with known T2DM not on insulin treatment at the time of hospitalisation for SARS-CoV-2 infection between April and March 2020 demonstrate that 35% of people with known diabetes required insulin as a new treatment during their hospitalisation." (PMID 35256883, 2022).
diabetes (continued). "It is these acids, not insulin, that raise the activity and mRNA and protein expression of CYP3A4, as demonstrated in vitro on HepG2 and Fa2N-4 cells that are incubated with the serum of rats with streptozotocin-induced diabetes." (PMID 36359206, 2022). "However, the relationship between insulin therapy and DHEA and β-HSD levels in patients with diabetes has not been reported." (PMID 35928897, 2022). "By far, the most frequent form of monogenic diabetes is MODY, which according to its historical definition is inherited in an autosomal dominant manner and occurs in lean individuals before the age of 25 years, with no need of insulin therapy." (PMID 35052457, 2022). "However, unlike insulin, the physiological function of CPR for improved glycemic control in diabetes is still controversial." (PMID 35229479, 2022). "Experiments have shown a chronic rise in insulin levels in MAFLD patients, regardless of whether or not they have diabetes, leading to decreased lung capacity in COVID-19 patients." (PMID 36531832, 2022). "The patient received diabetes education and testing for autoimmune diabetes (antibodies to glutamic acid decarboxylase (anti-GAD), islet cell antibodies (anti-ICA), and tyrosine phosphatase; C-peptide and insulin) revealed no remarkable results." (PMID 35402477, 2022). "This has caused the hypothesis that age-induced hyperactivity of mTORC1 plays a key role in the development of insulin resistance and diabetes, supported by data that showed that the absence of S6K1 improves insulin sensitivity and glucose homeostasis." (PMID 35534615, 2022). "We observed colocalization of SARS-CoV-2-NP with multiple INS+ β cells and non–insulin-producing islet cells in 1 male subject (COVID19-1), who was admitted with new-onset diabetes (nonfasting glucose > 300 mg/dL), demonstrating SARS-CoV-2 infection of β cells and other islet cells in this patient." (PMID 34241597, 2021). "Insulin secretion increased during co-infusion, compared with GIP alone or GLP-2 alone, but not with GLP-1 alone; this result highlighted the lack of GIP stimulus on insulin release in patients with diabetes." (PMID 35054422, 2021). "However, an increase in insulin levels also resulted in the overexpression of PHLPP1 itself, being probably involved in a regulating feedback loop that is lost in diabetes, for reasons that are not yet understood." (PMID 33920886, 2021). "In the study cohort, patients were not consuming medications other than insulin (ten under MDI, two under pump therapy) and had levels of diabetes control (mean HbA1C levels: 7.1%) corresponding to average levels achieved in pediatric diabetes conventions of care." (PMID 34512541, 2021). "By contrast, vitamin D supplementation did not produce clear improvements in blood pressure and insulin sensitivity in CVD patients, thus suggesting that the role of vitamin D in CVD, diabetes, or other cardiometabolic diseases could be inconclusive." (PMID 34836405, 2021). "All insulin users, age >30 years.T2DM sample mean age 63, male 56%Exclusion: patient without linkage to HES, pre-index period ≤180 days, hypoglycaemia before index, no diabetes classification, CV event at index." (PMID 33763024, 2021). "RYGB prevented hyperglycemia in 100% of HFD-fed NZO mice, suggesting that HFD accelerates the development of overt diabetes, which can be prevented by RYGB, and RYGB, but not SHAM-PF, preserves insulin+ cells, contributing to improved hyperglycemia in HFD-fed NZO mice." (PMID 34673835, 2021). "In 1467 participants (55.6 ± 9 years, BMI 29.3 ± 6 kg/m2) with normal glucose metabolism (46%), impaired glucose tolerance (22%) and without insulin dependent diabetes mellitus (32%), the estimated energy expenditure (EEE) was assessed by structured interviews, and insulin sensitivity was measured." (PMID 32867079, 2020).
diabetes (continued). "PPARγ is well known as a regulator of insulin sensitivity and TZD drugs ameliorate insulin resistance by reducing plasma glucose and they improve the lipidemic profile in type 2 diabetes (T2D) and in obese subjects without diabetes." (PMID 33198317, 2020). "In particular, a recent cluster analysis of TEDDY data implies that children who develop combinations of autoantibodies to insulin and islet antigen 2 (IA2) (with or without GAD65) within the first 2 years of life are likely to progress to diabetes within 5 years (i.e. before the age of 7 years)." (PMID 32172310, 2020). "Most commonly, eating disorders in people with diabetes take the form of disturbed eating behaviours (DEB) such as food restriction, binging and vomiting, laxative use and excessive exercise, which can occur with or without the presence of insulin misuse." (PMID 32967730, 2020). "This score includes the measurement of the liver fat content as determined by H-MRS, the presence or absence of the metabolic syndrome together with type 2 diabetes mellitus, aspartate aminotransferase (AST) levels, the AST:ALT ratio, and the fasting insulin serum level." (PMID 31394730, 2019). "This may be because the duration of diabetes in T1DM is usually longer than T2DM (P < 0.001) and the complete absence of insulin that leading to prolong glycation of the enzyme protein." (PMID 31372141, 2019). "It is particularly important to realize that type 2 diabetes (T2D) is connected with insulin resistance, which cannot be diagnosed without a fasting insulin test and a HOMA-IR assessment, which is still uncommon, and not included in the worldwide diabetes guidelines." (PMID 31428627, 2019). "Therefore, acting on the FXR might be a potential method to improve insulin and glucose sensitivity in diabetes mellitus (DM) and non-alcoholic fatty liver disease (NAFLD)." (PMID 31181641, 2019). "In addition, even though not insulin-dependent, stimulating glucose uptake by hepatocytes via the GLUT2 transporter is another important hepatic hypoglycaemic mechanism of interest in diabetes." (PMID 31516543, 2019). "They found that α cells and polypeptide-producing γ cells, obtained from pancreatic islet cells from deceased human donors with and without diabetes, can be lineage traced and reprogrammed by the transcription factors PDX1 and MAFA to produce and secrete insulin in a glucose-responsive manner." (PMID 31686269, 2019). "Type 2 diabetes (T2D), also known as “non-insulin-dependent diabetes mellitus” (NIDDM) or “adult-type diabetes”, begins with insulin resistance, and its progression may involve a lack of insulin." (PMID 31671732, 2019). "Reduced frequency of PSA testing after commencing use of insulin may reflect recommendations not to offer PSA testing to men with limited life expectancy due to chronic disease (eg, severe diabetes)." (PMID 31693126, 2019). "Also, ROC analysis was reported only for diabetes prediction [AUC = 0.642) and not for IGT and most importantly, potentially important confounders such as fasting glucose, insulin, HbA1c or inflammation markers were not taken into consideration." (PMID 30399195, 2018). "This may have biased our results as we did not adapt the EDE-Q for individuals with diabetes and we did not assess the diabetic specific DEB of insulin purging." (PMID 29744106, 2018). "The estimates (with adjustments for confounders) differed significantly across the subgroups according to hypertension, HDL cholesterol and triglycerides but not significantly across the subgroups not according to diabetes status, LDL cholesterol, hsCRP and insulin." (PMID 30133541, 2018). "Chronic overconsumption of fat and carbohydrates (e.g., glucose) elevates circulating insulin, leptin, FFA and triglyceride concentrations, with or without diabetes, thereby exposing the heart to toxic anabolic stimuli and an overabundance of oxidative substrates." (PMID 30344301, 2018).
diabetes (continued). "Hence, compared with those with new-onset diabetes and IFG participants, previously diagnosed diabetes without any control measures showed higher levels of FPG and HbA1c but lower levels of insulin and HOMA-IR." (PMID 30211231, 2018). "Type 2 diabetes mellitus (DM2) is a chronic noncommunicable disease that arises when the pancreas does not produce sufficient insulin and/or when the body cannot effectively use the insulin it produces, resulting in chronic hyperglycemia." (PMID 29764429, 2018). "It will be important to identify the neurotransmitters or neuropeptides that mediate the effects of Xen on insulin and glucagon release in humans because signaling pathways initiated by Xen rather than GIP fail early during the development of type 2 diabetes mellitus." (PMID 29466430, 2018). "Diabetes mellitus (DM), especially type 2 diabetes mellitus (T2DM), is referred to a metabolic disorder of multiple etiologies in which chronic hyperglycemia results from absent or inadequate pancreatic insulin secretion, with or without concurrent impairment of insulin action." (PMID 28317897, 2017). "Moreover, the usefulness of OGTT based IR or insulin-sensitivity indices, or glycated hemoglobin (HbA1C) for differentiating between CSX and CAD, who did not have known diabetes mellitus (DM), remains unexplored." (PMID 28194232, 2017). "In summary, we found that healthy FDR display higher glucose and insulin levels during an OGTT, higherserum triglycerides and a tendency towards disturbed β-cell dysfunction, when compared to subjects without a family history of diabetes." (PMID 28705209, 2017). "Outcomes were analysed according to the type of diabetes and, in the GDM group, whether or not diabetes was insulin-treated." (PMID 28197657, 2017). "However, more advanced prediction models, such as those including measurements of diabetes status (e.g. IFG and IGT) and related compounds such as insulin and adiponectin were not significantly improved by the addition of metabolomics data." (PMID 28692646, 2017). "The problem with discriminating T1D, whether insulin-dependent or non-insulin requiring (LADA), from Type 2 diabetes and from Maturity Onset Diabetes of the Young (MODY), can be helped by assessing the relative genetic contribution to each." (PMID 28829396, 2017). "Recent studies have reached the conclusion that fasting insulin levels during GH therapy might be slightly elevated in children with PWS, but this is transient and does not eventually progress to diabetes." (PMID 28854950, 2017). "Lactococcus lactis, another potent probiotic species used in our study, was recently reported to cure diabetes in non-obese diabetic mice, in combination with low-dose anti-CD3, through a series of actions including decline in insulin autoantibody positivity and stable reversal of hyperglycemia." (PMID 29228964, 2017). "While carvacrol did not have significant effect on the serum insulin level at the tested dose, carvone, citronellol, geniposide, geraniol, myrtenal and swertiamarin have all been shown to increase insulin level in the STZ-induced diabetes." (PMID 29267214, 2017). "Thus, we hypothesized that the diabetes observed in NOD.β2mKO.HHD.Ins2het mice was of an autoimmune nature, as is the case for the NOD.β2mKO.HHD parent strain, and not a deficiency in pancreatic insulin production due to the presence of only one functional copy of the Ins2 gene." (PMID 26824049, 2016). "Combination therapy with canagliflozin and insulin was investigated in a prescribed substudy of the canagliflozin Cardiovascular Assessment Study (CANVAS); however, it was not evaluated in Japanese patients with type 2 diabetes mellitus (T2DM)." (PMID 27316668, 2016). "Clinical studies have revealed that testosterone supplementation had a positive effect on glucose homeostasis in type 2 diabetes mellitus (T2DM), but did not address how testosterone supplementation affected insulin responsiveness in the liver, a key glucose homeostatic organ." (PMID 27941939, 2016).
diabetes (continued). "Fifty‐four unrelated probands were selected based on the following criteria: age of diagnosis ≤17 years, family history of diabetes in at least two generations, anti‐GAD/ICA negative, BMI<95.p and follow‐up with diet, oral antidiabetic drug or low‐dose insulin treatment (≤0·5U/kg/d)." (PMID 27256595, 2016). "Perhaps most importantly for the prostate cancer patient with diabetes or some degree of insulin insensitivity, muscle contraction-stimulated release of AMPK and the mitigation of serum glucose levels via cellular influx are independent of insulin sensitivity." (PMID 26977321, 2016). "Diabetes mellitus (DM) is a group of chronic medical conditions in which the body’s metabolism is deranged either due to absence or insufficient production of insulin or the body does not properly respond to insulin; producing a persistent hyperglycaemic state." (PMID 26429704, 2015). "Thus, the aim of the present study was to investigate the difference in first-phase insulin secretion and the effect of intensive insulin therapy on the improvement of β-cell function between T2DM patients with and without a FH of diabetes." (PMID 25574243, 2015). "While no direct role has been uncovered for PE in insulin secretion, we have recently found that inhibition of the GPR40 receptor, a therapeutically relevant target for the treatment of diabetes, results in the accumulation of CDP-ethanolamine, concomitant with reduction in lipid cycling in β-cells." (PMID 26107620, 2015). "Diabetes implications: For both diabetic and non-diabetic patients, lorcaserin treatment resulted in improvements in numerous glycaemic markers such FBG, fasting insulin, HbA1c and HOMA-IR." (PMID 25894803, 2015). "Second, we were unable to assess whether the joint effect of diabetes and IDE/HHEX genes on dementia is mediated by insulin resistance, because data on plasma insulin levels were not available in our study." (PMID 26173052, 2015). "In the present prospective study, the differences in first-phase insulin secretion and the effect of ITT on the improvement of β-cell function were investigated and compared in newly diagnosed T2DM patients with or without a FH of diabetes." (PMID 25574243, 2015). "Of those with diabetes, approximately 90% is type 2 diabetes or non-insulin-dependent diabetes mellitus (NIDDM) in which the body does not produce enough insulin or utilizes the available insulin inefficiently." (PMID 26600865, 2015). "However, the EDS-5 is not a diabetes-specific questionnaire and it is likely that the EDS-5 is insensitive to insulin omission/insulin purging as a means to lose weight." (PMID 25303963, 2014). "Any possible insulin effect is, therefore, mostly deleted in both such models, although there may be a lingering insulin production in STZ-induced diabetes, explaining why these rats survive without insulin supplementation over a period." (PMID 25216784, 2014). "Aim is to determine relationships of bilirubin with TSH, free T4 and free T3 in euthyroid subjects without type 2 diabetes mellitus (T2DM), and to assess whether such a relationship would be modified by the degree of insulin resistance." (PMID 24595410, 2014). "In this study, insulin sensitivity was not a criterion for diagnosing MHO, which is a potential limitation of our research; however, we attempted to minimize this error by including fasting blood sugar and the use of diabetes medication." (PMID 25394775, 2014). "Insulin therapy, which normalizes blood glucose without affecting the open KATP channel, prevented the changes in insulin- and glucagon-staining, β-cell ultrastructure and number of ins+/glu+ cells produced by 4 weeks of diabetes." (PMID 25145789, 2014). "Prevention and treatment of T2DM in Cambodia is limited as the public health services do hardly provide any diabetes care, T2DM is not included in the “basic package of health care” and oral anti-diabetic drugs (OAD) and insulin are not available in the whole country." (PMID 26208925, 2014).